HSPB8 (heat shock protein family B (small) member 8)
Diseases named in the same sentence as HSPB8 in open-access papers (continued):
Sharing a sentence is not in itself a finding about the gene and the disease.
scrapie (2 papers, 2010 to 2020). A fatal disease of the nervous system in sheep and goats, characterized by pruritus, debility, and locomotor incoordination. "Comparing the prp2 morphant with the mouse scrapie model revealed 5 genes in common: GFAP, CD9 antigen (CD9), solute carrier family 14 member 1 (SLC14A1), heat shock 22kDa protein 8 (HSPB8) and syndecan 4 (SDC4)." (PMID 21042590, 2010). "Similarly, autophagy activator genes HSPA8 [heat shock protein family A (Hsp70) member 8] and HSPB8 [heat shock protein family B (small) member 8] are upregulated in the CNS of sCJD-infected Tg340-PRNP129MM mice at clinical stage, sCJD patients, and naturally scrapie-infected sheep." (PMID 32984276, 2020).
Autoimmunity (1 paper, 2012). The occurrence of an immune reaction against the organism's own cells or tissues. "Both ICP10PK and H11/HspB8 were implicated in inflammatory processes that involve dendritic cells activation through Toll-like receptor-dependent pathways and may contribute to the onset of autoimmunity." (PMID 23056924, 2012). "However, additional studies are needed in order to better understand the possible interaction between H11/HspB8 and ICP10PK in inflammation and autoimmunity." (PMID 23056924, 2012).
autosomal-dominant distal hereditary motor neuropathy (1 paper, 2018). "Regarding HSPB8, K141E hot-spot mutation causes autosomal-dominant distal hereditary motor neuropathy (distal HMN type IIA, OMIM 158590), whereas its variant (K141N) causes Charcot–Marie–Tooth disease type 2L (CMT2L, OMIM 608673)." (PMID 30032358, 2018). "Here, we applied a Drosophila model to test the impacts of hot-spot mutations in the gene coding for HSPB8 that have been associated with two inherited human pathologies, the autosomal dominant dHMN (K141E), and CMT disease type 2L (K141N)." (PMID 30032358, 2018).
bladder tumors (1 paper, 2024). "Although HSPB8 was expressed at higher levels in high-grade bladder tumors than in low-grade tumors, the difference was not statistically significant." (PMID 38213722, 2024).
cervical cancer (1 paper, 2021). A primary or metastatic malignant neoplasm involving the cervix. "Finally, among the 12 autophagy biomarkers related to the survival of cervical cancer, based on literature search, we selected 6 genes (ATG4C, ATG4D, CD46, TP73, SERPINA1 and HSPB8) to verify their RNA expression in CC and normal cervical tissue samples." (PMID 34238288, 2021). "The experimental results confirm that ATG4D, CD46, TP73 and HSPB8 are decreased in cervical cancer, and the prognosis model shows a negative correlation with the risk score, it could be inferred that they had a protective effect on the occurrence and prognosis of cervical cancer." (PMID 34238288, 2021).
glaucoma (1 paper, 2008). Increased pressure in the eyeball due to obstruction of the outflow of aqueous humor. "There have been reports that several members of the sHSP gene family are differentially regulated in animal models of glaucoma, although no study has focused specifically on HspB8." (PMID 18671875, 2008).
ischaemic stroke (1 paper, 2020). "Heat shock protein B8 (HSPB8) has been recently reported to confer neuroprotection against against ischaemic stroke through maintaining BBB integrity." (PMID 32889520, 2020).
lung squamous cell carcinoma (1 paper, 2026). "Collectively, these results highlight ACE and HSPB8 as promising targets for lung squamous cell carcinoma treatment." (PMID 41490177, 2026).
lymph node metastasis (1 paper, 2021). "In addition, HSPB8 was highly expressed in depth of invasion, especially in T3 and T4 carcinomas, while patients with lymph node metastasis tend to show elevated HSPB8 expression." (PMID 33562660, 2021).
metastatic melanoma (1 paper, 2022). A melanoma that has spread from its primary site to another anatomic site. "Thus, it is likely that the loss of the HSPB8 protection contributes to the development of metastatic melanoma." (PMID 36400750, 2022).
motor neuron degeneration (1 paper, 2023). "In fact, mutations in genes coding for several HSPs (e.g., HSPB1, HSPB3, HSPB8 and DNAJB6) are causative not only for myopathies, but also for distal hereditary peripheral neuropathies, which are characterized by motor neuron degeneration." (PMID 40757567, 2023).
myotilinopathy (1 paper, 2016). "The CASA complex comprises the chaperones HSPB8/Hsp22 and HSPA8/Hsc70, and the co-chaperone BAG3 that were also over-represented in myotilinopathy aggregates." (PMID 26842778, 2016).
Onset (1 paper, 2025). The age group in which disease manifestations appear.
peripheral motor neuropathies (1 paper, 2022). "This is especially evident if HspB1, HspB3, and HspB8 are compared, all of them causing, when mutated, a similar spectrum of peripheral motor neuropathies." (PMID 35678958, 2022).
protein-folding disease (1 paper, 2025). "The growing evidence supporting both pharmacological induction and exogenous delivery of HSPB8 underscores its potential as a therapeutic target in diverse proteinopathies and neurodegenerative disorders and remains an important future direction for the field." (PMID 40243504, 2025). "Given its key role in preventing aggregation and favoring misfolded protein degradation, modulation, or induction, HSPB8 may represent a promising therapeutic approach in proteinopathies and protein-folding disease." (PMID 40243504, 2025).
schwannoma (1 paper, 2013). A benign, usually encapsulated slow growing tumor composed of Schwann cells. "In our series, 5 HSPs were deregulated (HSPA12A: 3.31-fold, p=4.34e-4; HSPA13: 2.54-fold, p=0.0035; HSPA4L: 2.38-fold, p=1.17e-4; HSPB6: −2.19-fold, p=5.76e-4; HSPB8: −3.77-fold, p=0.001), suggesting that the CAV1/HSPs interaction may also play a role in schwannomas." (PMID 23354516, 2013).
serous ovarian cancer (1 paper, 2021). "The pro-migratory activity of HSPB8 in cancer cell migration has also been described in a serous ovarian cancer cell line (SKOV3.ip1), in which overexpressed HSPB8 was found to increase TGF-α-induced ovarian cell migration." (PMID 33562660, 2021).
skin cutaneous melanoma (1 paper, 2022). "The comparison between skin cutaneous melanoma and matched normal samples clearly shows that human HSPB8 gene expression is downregulated in skin cutaneous melanoma." (PMID 36400750, 2022). "We initially analyzed HSPB8 gene expression in 103 samples of skin cutaneous melanoma patients of the TCGA study as well as 200 normal tissue (skin) of the GTEx studies available in OncoDB database." (PMID 36400750, 2022).
stomach adenocarcinoma (1 paper, 2019). "In the stomach adenocarcinoma dataset, strong positive correlations in gene expression were identified between members of the small HSP family, including HSPB2, HSPB5 (CRYAB), HSPB6, HSPB7 and HSPB8, as well as the HSP40 family member DNAJB5, with superoxide dismutase (SOD3)." (PMID 30578123, 2019).
subarachnoid hemorrhage (1 paper, 2022). A serious neurological disorder characterized by intracranial hemorrhage into the subarachnoid space. "It is reported that exogenous HSPB8 significantly conveys neuroprotection via attenuation of mitochondrial damage partly by suppressed drp1-mediated mitochondrial fission through AMPK-PGC1α signaling pathway after subarachnoid hemorrhage (SAH)." (PMID 35958024, 2022).
type 1 diabetes (1 paper, 2021). "HSPB8 is known to prevent oxidative tissue damage and its expression in serum is used as a biomarker for virus induced type 1 diabetes." (PMID 33472578, 2021).
vacuolar myopathy (1 paper, 2021).
viral infection (1 paper, 2017). "The increased expression of the HSPB8 and DNAJC5B genes observed in the qPCR array indicated that these proteins either promote HCV replication or were expressed by the cells due to stress resulting from the viral infection." (PMID 29182667, 2017). "There are no data that links the HSPB8 protein to a cellular defence mechanism for viral infections." (PMID 29182667, 2017).
cancer (35 papers, 2011 to 2026). A tumor composed of atypical neoplastic, often pleomorphic cells that invade other tissues. "Subsequently, we employed a univariate Cox regression model to analyze the association between the expression levels of ACE and HSPB8 in pan-cancer samples and patient survival." (PMID 41490177, 2026). "HSPB8 variants have been also described in cancer (e.g., W51C and P173H), in which HSPB8 role has been recently extensively reviewed." (PMID 35281256, 2022). "In this review, we will discuss the molecular mechanism underlying HSPB8 roles in normal and cancer conditions." (PMID 33562660, 2021). "Several studies have shown that an abnormal expression of HSPB8 in cancer cells may be associated with tumor progression." (PMID 33562660, 2021). "HspB8 is regulated by estrogen and can augment cancer cell progression by estrogenic stimuli, suggesting HspB8 might be a target associated with ER-positive tumors." (PMID 32927696, 2020). "Therefore, it is important to deeply investigate the molecular mechanisms underlying human HSPB8 activities in order to evaluate in which type of cancer its induction/activation or downregulation/inactivation may represent a potential treatment." (PMID 33562660, 2021). "Similarly, HSPB8 can act either as a tumor-promoting or tumor-suppressive factor depending on cancer type and mutational background, suggesting that differential pathway activation, feedback loops, and cell-type–specific metabolic or epigenetic states may underlie these contrasting effects." (PMID 41490177, 2026). "As one of the players in CASA, HSPB8 has been gradually confirmed to promote the development of various cancers." (PMID 39215616, 2024). "By modulating gene expression, HSPB8 potentially governs the trajectories of oncogenic and tumor-suppressive proteins, dictating cancer evolution and progression." (PMID 38213722, 2024). "Of interest, these data are in line with those obtained in other type of cancers, demonstrating that HSPB8 repressed hepatocarcinoma progression and migration by downregulation of PI3K/Akt signaling pathway." (PMID 36400750, 2022). "It is known that HSPB8 is involved in autophagy, and that autophagy is deeply involved in tumorigenesis and cancer progression." (PMID 36400750, 2022). "All data reported in this review suggest that HSPB8 is deeply involved in the modulation of the appearance and the progression of many types of cancer in humans." (PMID 33562660, 2021). "Collectively, the knowledge on HSPB8 role in cancer demonstrates that this protein plays a different role related to the tumor context." (PMID 33562660, 2021). "The basic mechanisms involved in anti- and pro-tumoral activities of HSPB8 are deeply discussed together with the pathways that modulate HSPB8 expression, in order to outline molecules with a beneficial effect for cancer cell growth, migration, and death." (PMID 33562660, 2021). "In cancer cells, HSPB8 is differentially expressed and displays a dual and opposite role depending upon the type of tumor considered." (PMID 33562660, 2021). "Since a direct relationship between HSPB8 expression and inflammatory cell death was not investigated, further studies should be addressed to determine the role of HSPB8 in cancer inflammation." (PMID 33562660, 2021). "Other potent HSPB8 inducers are several proteasome inhibitors, some of which are currently used as therapeutic options against cancer, due to their ability to activate autophagy." (PMID 33562660, 2021). "In stressful conditions (e.g.: hypoxia or nutrient deprivation), HSPB8 is upregulated, and by facilitating autophagy, mediates amino acids recycle enhancing cancer cell capability to survive under unfavorable conditions." (PMID 28060751, 2017). "The cell-cycle regulatory potential of H11/HspB8 in normal cells, its dysfunctional state in cancer cells, and its ability to induce tumor cell death upon restored expression identify H11/HspB8 as a tumor suppressor." (PMID 23056924, 2012).
cancer (continued). "HSPB8 has shown potential as a prognostic biomarker for cancer in numerous studies." (PMID 41490177, 2026). "Tissue-specific regulation and embryonic origin may further contribute to the context-dependent roles of ACE and HSPB8 across cancers, warranting additional mechanistic investigation." (PMID 41490177, 2026). "Notably, HSPB8 overexpression is discerned in specific cancer types, especially those exhibiting elevated metastatic prowess, a scenario often correlated with a grim prognosis." (PMID 38213722, 2024). "HSPB8 expression and function in different cancers are different." (PMID 36982249, 2023). "The expression of HSPB8 varies in different types of cancer cells." (PMID 37233869, 2023). "Related studies suggest that although the molecular mechanism of HSPB8 in cancer requires deeper investigation, HSPB8 may be a significant factor in the initiation and progression of tumors and may be a biomarker for the treatment of certain types of tumors." (PMID 36983630, 2023). "In these cancer types, HSPB8 promotes proliferation and suppresses apoptosis." (PMID 35330734, 2022). "HSPB1 is frequently upregulated in BC, wherein it promotes cancer cell growth and metastasis by inducing the SUMOylation of HSPB8 and increasing its expression, and SPINT1 was highly expressed in the HER2-positive type, with a relatively high rate in node-positive patients." (PMID 36428562, 2022). "In cancer, HSPB8 has anti- or pro-tumoral action depending on tumor type." (PMID 36400750, 2022). "In cancer, HSPB8 exerts dual and opposite role depending on its expression levels and on cell type." (PMID 36400750, 2022). "In addition, studies have reported that HSPB8 exerts both beneficial and detrimental effects on cancer proliferation, invasion, and migration." (PMID 35330734, 2022). "As detailed above, HSPB8 has a controversial dual role in cancer." (PMID 33562660, 2021). "However, as extensively discussed, HSPB8 activity can be either beneficial or detrimental for cancer cell growth, migration, and death." (PMID 33562660, 2021). "Furthermore, it must be considered if these tumors have been previously treated with chemotherapeutic agents that have impacted on HSPB8 expression, allowing them to develop resistant cancer cell clones." (PMID 33562660, 2021). "On the other hand, HSPB8 SUMOylation at Lys-106 in MCF-7 cancer cells has been recently described." (PMID 33562660, 2021). "Another sHSP protein, HspB8, has been recently identified to enhance cancer progression." (PMID 32927696, 2020). "Additionally, HSPB8 has contrasting roles in different cancers." (PMID 37233869, 2023). "Thus, the role of HSPB8 in cancer has attracted increasing attention." (PMID 35330734, 2022). "Given the critical role of the tumor microenvironment in cancer progression, and because tumor-infiltrating immune cells are an integral part of the tumor microenvironment, we investigated the relationship between HSPB8 expression status and immune infiltration in BC." (PMID 35330734, 2022). "Here, we will briefly summarize how and when HSPB8 may act as a pro-cancer or anticancer agent." (PMID 33562660, 2021). "Therefore, both HSPB8 inducers and repressors could be of interest against cancer, depending upon the specific tumor to be treated." (PMID 33562660, 2021). "This suggests a potential mutual regulatory dynamic between HSPB8 and HSP27, emphasizing the need for further comprehensive studies to uncover potential therapeutic avenues in cancer treatment." (PMID 38213722, 2024). "There is generally a tight correlation between HSPB8 and MMP-9 expression, with higher invasive and metastasizing activity in HSPB8 high-expression cancer cells." (PMID 33562660, 2021). "The initial category, containing ANKHD1, ATXN8OS, HSPB8, LSM7, MAFB, and TCTN2, is involved in the direct regulation of cancer cell proliferation, apoptosis, and cancerization." (PMID 34235216, 2021). "We constructed a pan-cancer expression profile for the ACE and HSPB8 genes." (PMID 41490177, 2026).
cancer (continued). "Neither ACE nor HSPB8 has been systematically explored in carcinoma, underscoring the importance of further analyses and knockdown experiments in LUSC cells." (PMID 41490177, 2026). "Therefore, HscA8/Hsp70 and HspB8/Hsp22 compex and CASA play an significant function in protein quality control of cancer cells." (PMID 35155422, 2022). "HSPB8, Heat shock protein 22 (HSP22), known as H11 kinase, E21G1, is a member of the small HSP family of proteins containing an α-crystalline domain and has been demonstrated to have a protective effect against various conditions including oxidative stress, aging, cancer, and apoptosis." (PMID 35958024, 2022). "The role of HSPB8 has not yet been analyzed in cancer inflammation." (PMID 33562660, 2021). "Despite the fact the mechanisms of HSPB8-mediated CASA activation in tumors need further studies, HSPB8 could represent an important factor in cancer induction and progression and it may be a potential target for anticancer treatment in specific types of cancer." (PMID 33562660, 2021). "Heat shock protein 22 (HSP22) known as H11 kinase, E21G1, and HSPB8 is a member of the small HSP family of proteins containing a α-crystalline domain and has been demonstrated to have protective effect against various conditions including oxidative stress, aging, cancer, and apoptosis." (PMID 28052764, 2017). "However, despite the many findings in recent years that have contributed to understanding the mechanism of action of HSPB8 and HSPB1 in response to proteotoxic events, some aspects of their regulation and function, as well as its implication in human cancer, remain partially unknown." (PMID 36233058, 2022). "Particularly, the expression of INHBA, HSP90AA1 and EIF2AK2 in ESCC cancer tissues was significantly higher than that in normal tissues, while the level of LRRK2 and HSPB8 in ESCC tissues was remarkably lower as compared to the normal tissues." (PMID 39006030, 2024).